XDH (xanthine dehydrogenase)
Diseases named in the same sentence as XDH in open-access papers (continued):
Sharing a sentence is not in itself a finding about the gene and the disease.
ischemia (58 papers, 2004 to 2025). A hypoperfusion of the BLOOD through an organ or tissue caused by a PATHOLOGIC CONSTRICTION or obstruction of its BLOOD VESSELS, or an absence of BLOOD CIRCULATION. "During ischemia reperfusion (IR), calcium overload and reduced ATP synthesis cause XO activation from xanthine dehydrogenase and ROS production." (PMID 33673423, 2021). "Currently, reperfusion injury is thought to hinge on two critical events occurring during ischemia: energy failure caused by retinal blood flow disturbance and conversion of xanthine dehydrogenase to xanthine oxidase." (PMID 30682118, 2019). "Local ischemia causes ATP to be broken down into hypoxanthine and xanthine dehydrogenase that are then converted into xanthine oxidase." (PMID 29880057, 2018). "In the xanthine oxidoreductase system, xanthine dehydrogenase is converted to xanthine oxidase, which generates ROS during ischemia, and ROS production is further promoted by the re-entry of oxygen during reperfusion." (PMID 40296757, 2025). "During ischemia, ATP is degraded to hypoxanthine, and xanthine dehydrogenase (XDH) is converted to xanthine oxidase (XO), which upon reperfusion reacts with molecular oxygen to produce reactive oxygen species (ROS) such as superoxide and hydrogen peroxide." (PMID 41002405, 2025). "During ischemia, a large amount of Ca2+ enters the cell to activate the Ca2+-dependent proteolytic enzyme, which converts xanthine dehydrogenase into xanthine oxidase in a large amount." (PMID 36091169, 2022). "It was also observed that the conversion of xanthine dehydrogenase to xanthine oxidase (a process considered to be the major source of superoxide anion) in the heart during ischemia was inhibited by FBP23-25." (PMID 32667586, 2020). "On the other hand, an increase in [Ca2+]i during ischemia induces the conversion of xanthine dehydrogenase to xanthine oxidase and subsequently results in generating superoxide radicals." (PMID 23936799, 2013). "Under low O2 conditions, such as ischemia, the enzyme xanthine dehydrogenase displaces xanthine oxidoreductase due to lower levels of ATP, which induces the formation of ROS during the conversion of hypoxanthine to uric acid, which ultimately further aggravates the oxidative environment." (PMID 33622196, 2021).
Insulin resistance (45 papers, 2004 to 2025). Increased resistance towards insulin, that is, diminished effectiveness of insulin in reducing blood glucose levels. "In fact, the presence of elevated serum urate level is a biomarker and risk factor for fatty liver disease, and greater XDH activity has been suggested as a causative factor for the development of insulin resistance and NAFLD through increasing oxidative stress via production of hydrogen peroxide." (PMID 33345777, 2020).
renal failure (34 papers, 1998 to 2025). "Human patients with mutations in XDH develop xanthinuria which can lead to xanthine stones in the kidney, recurrent urinary tract infections, and renal failure." (PMID 40991662, 2025). "Xanthinuria type I is a rare genetic disease caused by a mutation in the XDH gene, and is characterised by kidney stones (urolithiasis), urinary tract infections, and rarely kidney failure." (PMID 38386685, 2024). "Genetic deletion of the XDH gene in rats induces kidney damage, renal failure, and stunted growth and development." (PMID 40949127, 2025). "Our studies demonstrate that ENU mutagenesis may be useful for generation of mouse models for renal failure, and that this RENF model may help to elucidate further mechanisms of renal fibrosis and the in vivo role of XDH and uric acid." (PMID 23024809, 2012). "However, both XDH ki and XO ki mice have a normal phenotype and growth, and in particular no sign of renal failure and premature death, which suggests that XOR mutant enzymes expressed normally and sufficiently with normal physiological function in the XOR gene-modified mice." (PMID 31659168, 2019). "Taken together, our results suggest that low expression of XDH, CYP2E1, and SULT1A1, combined with the absence of renal AhR, may explain the low level of renal insufficiency observed in AhR−/− mice in the adenine-induced CKD model." (PMID 32260098, 2020).
xanthinuria (30 papers, 2010 to 2025). A metabolic metabolic disorder characterized by excess urinary excretion of the purine base xanthine. "Mutations in the xanthine dehydrogenase can cause xanthinuria and the accumulation of xanthine kidney stones in humans." (PMID 40991662, 2025). "Xanthinuria, an inborn error of purine metabolism, is caused by inactivation of xanthine dehydrogenase (XDH), the terminal enzyme in purine catabolism that oxidizes hypoxanthine to xanthine and xanthine to uric acid." (PMID 40991662, 2025). "In UND_6 (15 days), with mild xanthinuria, low uric acid, and hyperglycinuria, RNA-seq revealed XDH expression changes associated with xanthinuria type I (OMIM #278300)." (PMID 40576830, 2025). "Genetic causes of xanthinuria with NL and/or NC consist of Xanthinuria (XDH and MOCOS genes) and Molybdenum cofactor deficiency (MOCS1 and MOCS2 genes)." (PMID 38606357, 2024). "Of note, this variant located at a CpG mutation hot spot in the XDH gene was previously reported in a compound heterozygous Czech xanthinuria case." (PMID 34356852, 2021). "We describe a novel point mutation in the XDH gene in homozygosis found in a patient with very low serum and urine levels of uric acid, together with xanthinuria." (PMID 37360896, 2021). "One good example of modeling kidney disease in flies is xanthinuria type one caused by loss of enzyme xanthine dehydrogenase (XDH)." (PMID 32984330, 2020). "Inherited xanthinuria, an autosomal recessive condition can be caused by deficiency of the (XDH), or by double deficiency of XDH and aldehyde oxidase or by lack of molybdenum cofactor, which is an essential cofactor for the function of several enzymes." (PMID 28282408, 2017). "Loss-of-function mutations of XDH in man cause hereditary xanthinuria, which is characterised by very low or undetectable plasma uric acid levels." (PMID 23024809, 2012). "XDH mutations in man cause xanthinuria with undetectable plasma uric acid levels and three RENF mice had plasma uric acid levels below the limit of detection." (PMID 23024809, 2012). "Hypouricosuria, low urinary excretion of urate, is a symptom of xanthinuria that is caused by xanthine dehydrogenase (XDH) deficiency, which is consistent with the deficient model's inability to excrete urate." (PMID 20957118, 2010). "There are two types of human xanthinuria; type I is caused by mutations in the gene encoding the xanthine dehydrogenase enzyme and type II is caused by mutations in genes essential for the synthesis of the molybdenum cofactor, an essential prosthetic group for XDH." (PMID 40991662, 2025). "Classically, Type I xanthinuria is caused by a mutation in XDH/XO gene mapped to chromosome 2p23.1, whereas Type II xanthinuria is caused by deficits of XDH/OX and aldehyde oxidase (AO) caused by mutations in molybdenum cofactor sulfurase gene (MOCOS) localized on chromosome 18q12.2." (PMID 30157195, 2018). "Thus, xanthinuria is a disease of hypouricemia caused by loss of XDH/XOR." (PMID 35327453, 2022). "Disorders of uric acid metabolism had 12 genetic results on xanthinuria (XDH and MOCOS) and renal hyperuricemia (SLC22A12) genes, affecting 11 patients (10%)." (PMID 40126616, 2025). "Traditionally, the type of hereditary xanthinuria has been stablished by allopurinol loading test or liver biopsy, because xanthine dehydrogenase/ xanthine oxidase (XDH/XO) activity in humans is expressed only in the small intestine and liver." (PMID 30157195, 2018). "Iatrogenic xanthinuria, instead, results from treatment with allopurinol, a stereoisomer of hypoxanthine, which acts as a competitive inhibitor of XDH." (PMID 28282408, 2017). "Very low levels of XDH activity in the duodenal mucosa would confirm the diagnosis of xanthinuria." (PMID 37360896, 2021). "Classical xanthinuria is a rare autosomal recessive metabolic disorder characterized by lack of xanthine dehydrogenase activity that often manifests as xanthine urolithiasis and risk of drug toxicity." (PMID 32071838, 2020).
xanthinuria (continued). "Classical xanthinuria is a rare autosomal recessive metabolic disorder due to impaired xanthine dehydrogenase (XDH) activity resulting in lack of uric acid (UA) formation and accumulation of its precursors xanthine and hypoxanthine." (PMID 32071838, 2020). "The majority of naturally occurring mutations of the human gene XDH, are associated with reduced or completely absent xanthine oxidoreductase (XOR) activity, leading to a disease known as classical xanthinuria, which is due to the accumulation and excretion of xanthine in urine." (PMID 39765766, 2024). "Classical xanthinuria is a rare, autosomal recessive metabolic disorder characterized by impaired xanthine dehydrogenase (XDH; EC 1.17.1.4) activity that results in a lack of uric acid (UA) formation and accumulation of its precursors, xanthine (X) and hypoxanthine (HX)." (PMID 34356852, 2021).
breast carcinoma (28 papers, 2002 to 2024). "We have found six polymorphisms in OGG1, GPX6, SOD3, TXN and XDH genes significantly associated with predisposition to breast cancer." (PMID 25416100, 2014). "This one is the first study that shows a relationship between polymorphisms on the GCLC and XDH genes and the survival outcome in breast cancer patients." (PMID 23443115, 2012). "Additionally, increased expression of xanthine dehydrogenase was associated with a better outcome for breast cancer patients." (PMID 38947399, 2024). "Indeed, it has been reported that decreases in XDH activity levels are associated with poor prognoses for cancers, including breast cancer, gastric cancer, ovarian cancer, non-small-cell lung cancer and colorectal cancer." (PMID 34496841, 2021). "Moreover, the low expression of XDH was associated with poor prognoses in various types of cancers, including colorectal cancer, early-stage gastric cancer, breast cancer, ovarian cancer, and hepatocellular carcinoma (Chen G.-L." (PMID 35664305, 2022). "Studies have shown that in liver, kidney, and breast cancer tissues, the expression of XDH is significantly lower than in normal tissues, purine catabolism is severely impaired, and anabolic enzymes are increased." (PMID 35693733, 2022). "Previous data from our group relate the polymorphisms rs1052133 on the OGG1 gene, rs207454 on the XDH gene and rs3736729 on the GCLC gene to susceptibility to breast cancer." (PMID 23443115, 2012). "Previous studies of our group have associated polymorphisms on genes related to oxidative stress (rs3736729 on GCLC and rs207454 on XDH) and DNA damage repair (rs1052133 on OGG1) with a predisposition to develop breast cancer." (PMID 23443115, 2012). "Differential expression of XDH gene modulated the migration of human breast cancer cells." (PMID 32315343, 2020). "According to alcohol metabolism-involved genes, three were up-regulated (ITGA5, CBS, and SOD2), and six were down-regulated (XDH, XRCC1, MTHFR, CYP1B1, XPC, and GSTP1) among women who died for breast cancer." (PMID 39125744, 2024). "The prognostic potential of XDH mRNA expression was also significant in certain other cancers, including HCC, breast cancer, kidney or bladder carcinoma, gastric cancer, mesothelioma, lung cancer, and ovarian cancer." (PMID 34496841, 2021). "Three genes were up-regulated (i.e., ITGA5, CBS, and SOD2), while six were down-regulated (i. e, XDH, XRCC1, MTHFR, CYP1B1, XPC, and GSTP1) among individuals who died of breast cancer." (PMID 32078659, 2020). "This work suggests that unfavorable genetic variants in the rs207454 (XDH) and rs3736729 (GCLC) polymorphisms may act as predictors of the outcome in negative progesterone receptor and negative estrogen receptor breast cancer patients, respectively." (PMID 23443115, 2012). "Unfavorable genetic variants in the rs207454 (XDH) and rs3736729 (GCLC) polymorphisms may act as predictors of outcome in negative progesterone receptor and negative estrogen receptor breast cancer patients, respectively." (PMID 23443115, 2012). "In addition, high XDH mRNA expression was also correlated with better OS in bladder carcinoma (HR 0.69, 95% CI 0.52 to 0.93, P = 0.015) and ovarian cancer (HR 0.87, 95% CI 0.76 to 0.99, P = 0.031) and better RFS in breast cancers (HR 0.77, 95% CI 0.69 to 0.86, P = 1.7e−6)." (PMID 34496841, 2021).
Stroke (25 papers, 2009 to 2025). Sudden impairment of blood flow to a part of the brain due to occlusion or rupture of an artery to the brain. "Simultaneously, there is a conversion of xanthine dehydrogenase to XO, which is crucial in post-stroke complications." (PMID 35603179, 2022). "Its molecular docking with targets such as XDH and PNP showed stable binding energy, suggesting that it participates in the pathological process of stroke by regulating purine metabolism and oxidative stress." (PMID 40950576, 2025).
Sepsis (20 papers, 2006 to 2025). Sepsis is defined as life-threatening organ dysfunction caused by a dysregulated host response to infection. "For prioritization of sepsis-associated causal variants, especially those noncoding XDH variants, we applied multiple tools integrating various genomic and epigenomic annotations to elucidate multiple aspects of biological functionality of XDH variants." (PMID 37415141, 2023). "This is the first study reporting an association between XDH polymorphisms and sepsis and sepsis-associated ARDS." (PMID 37415141, 2023). "Multifaceted functions of prioritized XDH variants, as suggested by various functional annotation tools, support their potential causality in sepsis." (PMID 37415141, 2023). "In summary, this is the first report to confirm that genetic markers in XDH are associated with sepsis and sepsis-associated ARDS in two diverse populations." (PMID 37415141, 2023). "We hypothesized that XDH SNPs may represent risk factors for the development of sepsis and associated organ failure by affecting tissue XOR activity, thus serving as biomarkers of disease severity and outcome." (PMID 37415141, 2023). "Multiple lines of evidence were discovered supporting our hypothesis that prioritized variants identified in our study could affect XDH expression and/or function, therefore influencing the severity and outcome of sepsis." (PMID 37415141, 2023). "We examined whether single nucleotide polymorphisms (SNPs) in the XDH gene (encoding XOR) might influence susceptibility to and outcome in patients with sepsis." (PMID 37415141, 2023). "However, we were unable to explore the genotype by environment (GxE) interactions in our study to confirm the possible modifying effects of local tissue/cell type specific environment (e.g., systemic inflammation) on XDH genetic risk factors in sepsis." (PMID 37415141, 2023). "Regarding blood UA levels, there may be a relationship between increased blood XDH levels due to sepsis and increased blood UA levels caused by the action of this enzyme, as well as effects on renal function and reduced body fluid volumes caused by dehydration." (PMID 37762160, 2023). "The levels of enzymes LDH, AST, and ALT increase as they are released into the blood from cells that are breaking down, and we believe that blood XDH levels rise through a similar mechanism, that is, due to organ injury accompanying sepsis." (PMID 37762160, 2023). "We also observed a positive correlation with the SOFA score, an indicator of disease severity in patients with sepsis, and a clear relationship between XDH levels and death from sepsis, with patients who died exhibiting persistently high XDH levels." (PMID 37762160, 2023). "However, in the sepsis patients in this study, blood XDH levels were positively correlated with blood UA levels but negatively correlated with blood 8-OHdG levels." (PMID 37762160, 2023). "The results of this study indicate blood XDH levels correlate with the severity of sepsis as indicated by the SOFA score and may be a prognostic factor for poor prognosis." (PMID 37762160, 2023). "Although our findings suggest that XDH variants are risk factors for sepsis, it deserves further validation in non-white cohorts with a larger sample size of sepsis cases." (PMID 37415141, 2023). "However, blood XDH levels increased in patients with severe sepsis, and there was a positive correlation with Cr and a negative correlation with eGFR." (PMID 37762160, 2023). "There are still few reports in the literature supporting a role for XO in the pathogenesis of human sepsis We believe that there is a need to analyze uric acid and XDH levels in different physicochemical situations and at different tissue and organ levels to be needed." (PMID 37762160, 2023). "Patients who died had persistently high blood XDH levels, which were related to death from sepsis." (PMID 37762160, 2023).
Sepsis (continued). "In addition, a negative correlation was observed between blood XDH levels and blood 8-OHdG levels, suggesting that in patients with sepsis, UA increases due to the rise in blood XDH, and this may play a role in reducing oxidative stress within the body." (PMID 37762160, 2023). "Therefore, for patients with sepsis, it is possible that an increase in blood XDH levels could be used as a pathophysiological biomarker to predict sepsis outcomes." (PMID 37762160, 2023). "The results demonstrated a positive correlation between blood XDH levels and SOFA scores, which are related to sepsis severity." (PMID 37762160, 2023). "We genotyped 28 tag SNPs in XDH gene in the CELEG cohort, including 621 European American (EA) and 353 African American (AA) sepsis patients." (PMID 37415141, 2023).
myocardial ischemia (18 papers, 2012 to 2024). A disorder of cardiac function caused by insufficient blood flow to the muscle tissue of the heart. "For example, xanthine oxidase (XO), which represents an oxidized form of xanthine dehydrogenase (XDH), forms in damaged tissues, including rat hearts with myocardial ischemia." (PMID 32290431, 2020).